GATA3 (GATA binding protein 3)
Diseases named in the same sentence as GATA3 in open-access papers (continued):
Sharing a sentence is not in itself a finding about the gene and the disease.
bladder cancer (continued). "The proportion of cancer cells positively stained for the PD-L1 membrane expression was statistically higher in GATA3-positive high grade primary NMIBCs (n = 8) than in low grade bladder carcinomas (n = 12), with average values of 26.8% vs. 16.3%, respectively (p = 0.017)." (PMID 33238591, 2020). "In order to facilitate molecular subtyping of bladder cancer in primary care centers, we analyzed the protein expressions of signature luminal (GATA3) and basal (KRT5/6) markers by immunohistochemistry, which identified molecular subtypes in over 80% of the cases." (PMID 32546765, 2020). "Thus, 26.8 ± 1.8% of cells of high-grade GATA3-positive relapsed bladder cancer expressed CD8+; in low-grade tumors, 21.7 ± 1.5% of cells represented stromal immune microenvironment." (PMID 32455829, 2020). "Likewise, GATA-3 gene expression in patients with low- and medium-grade cancers was significantly higher than that in patients with high-grade bladder carcinomas (p = 0.001)." (PMID 27237631, 2016). "We observed the downregulation of GATA3 already after 2 weeks of BBN treatment as well as in tumors, suggesting that dysregulation of GATA3 might be an early event during bladder cancer development in mice and this finding is in line with the high-grade invasive phenotype of BBN-induced tumors." (PMID 31779626, 2019). "Using real-time PCR to asses the gene expression of GATA3 and T-bet, a reduced Th2 phenotype (decreased GATA3 expression) correlated with disease aggressiveness (high-grade tumors and muscle-invasive status) and a poor cancer-specific survival in bladder cancer." (PMID 28005163, 2017). "In contrast, the expression of GATA-3 and Bcl-6 in non-invasive carcinoma (p = 0.008 and p = 0.0003) and in patients with low- and medium-grade cancers (p = 0.001 and p < 0.0001) is significantly higher than in invasive bladder tumors and in patients with high-grade bladder carcinoma, respectively." (PMID 27237631, 2016). "In five bladder cancer datasets (TCGA-MIBC, GSE13507, GSE48075, GSE32894, and GSE48276), ERBB2 was highly positively correlated with GATA3 and FOXA1 but negatively correlated with CD44 and KRT5, suggesting that ERBB2 is a luminal marker to some extent." (PMID 39840049, 2024). "This study aimed to classify bladder cancer subtypes using a panel of IHC markers (CK5/6 and CD44 for basal; GATA3 and CK20 for luminal) widely used in surgical pathology." (PMID 39768377, 2024). "Exhausted T cells of urinary bladder cancer highly expressed PD-1 and GATA-binding protein 3 (GATA3)." (PMID 38884843, 2024). "Functional validation of the dataset confirmed GATA3, SPT6, and the cohesin complex components SMC1A, and RAD21, as permissive upstream positive regulators of PPARG gene expression in luminal bladder cancer." (PMID 37250326, 2023). "Previous work showed that the three master Luminal TFs (FOXA1, GATA3, and PPARG) had to be perturbed simultaneously to induce a cell identity switch from luminal to basal in bladder cancer cell lines." (PMID 36944729, 2023). "We also assessed molecular subtypes using immunohistochemistry (IHC) with luminal (GATA3 and CK20) and basal (CK5/6) markers in our primary tumours (n = 13) and bladder cancer cell lines (n = 7)." (PMID 36944729, 2023). "In bladder cancer, GABPA activates the Fox1A and GATA3 genes, thereby promoting cancer cell differentiation." (PMID 35549739, 2022). "In a recent study on subtype-specific chromatin states in bladder cancer, the pioneer factors FOXA1 and GATA3 were each found to serve as “loop anchors”." (PMID 35902807, 2022). "Among the top DMRs, we note many overlapping with genes known to be involved in bladder cancer, such as FGFR3, GATA3, KRT15, and KRT5." (PMID 33397444, 2021). "Twenty lines of patient-derived xenografts (PDXs) of relapsed high-PD-L1(+) GATA3/CR5/6-negative NMIBC were developed, of which 10 lines represented high-grade tumors and the other ones, low-grade bladder cancer." (PMID 34576020, 2021).
bladder cancer (continued). "This indicated that GATA3 and KRT5/6 immunohistochemical staining is the most effective classifier for prediction of luminal and basal molecular subtypes of bladder cancer." (PMID 32546765, 2020). "In BC cell lines, studies by others have shown that have shown that GATA3 and FOXA1 cooperate with PPARγ activation to drive the differentiation of a basal bladder cancer subtype to a more differentiated luminal subtype." (PMID 32822399, 2020). "We concluded that the immunohistochemical staining with GATA3 and KRT5/6 is a simple classifier of molecular subtypes of bladder cancer which is effective in over 80% of the cases." (PMID 32546765, 2020). "Among the set of immunohistochemical markers, GATA3 and KRT5/6 have emerged as an effective surrogate molecular classifier of bladder cancer that correctly identified the molecular subtypes in over 80% of the cases." (PMID 32546765, 2020). "We evaluated the clinical efficacy and prognosis of muscle-invasive bladder cancer according to the basal/squamous-like (BASQ) classification system based on immunohistochemical staining [CK5/6(+), CK14(+), GATA3(−), and FOXA1(−)]." (PMID 31500577, 2019). "However, opposite directions were also noticed with higher expression level in tumors (e.g., bladder cancer, cervical squamous cell carcinoma) or in normal tissues (e.g., kidney cancer), indicating the important and heterogeneity role of GATA3 in tumorigenesis for different types of cancer." (PMID 28415601, 2017). "Using the molecular subtype assignments, and our own RNA-seq analysis, we found overexpression of GATA3 and FOXA1 cooperate with PPARɣ activation to drive transdifferentiation of a basal bladder cancer cells to a luminial phenotype." (PMID 27924948, 2016). "Since tretinoin is established as a differentiation therapy in acute leukemia, we sought to determine whether tretinoin treatment could induce the expression of GATA3 and FOXA1, which are key markers driving the luminal phenotype of bladder cancer." (PMID 38539513, 2024). "The expression of PLK1, GATA3, and CD40 were even related to the prognosis of bladder cancer." (PMID 36425941, 2022). "CK5-positive/GATA3-negative cells are characteristic of the so-called basal cell type of bladder cancer that can be identified consistently in several subtyping approaches for bladder cancer." (PMID 30523270, 2018). "Therefore, while we must be cautious in how we interpret this data, our approach validates the importance of PPARɣ and additionally shows a direct impact of GATA3 and FOXA1 on the expression of markers of the luminal molecular subtype of bladder cancer." (PMID 27924948, 2016). "Additionally, the bladder cancer was also positive for GATA3, 34βE12, and CK7 while negative for p63." (PMID 40917856, 2025). "Therefore, the employment of GATA3 in the determination of TME phenotypes and bladder cancer subtypes has focused on GATA3 as a promising candidate for personalized medicine for better management of bladder cancer." (PMID 39768217, 2024). "Similarly, PPARG did not emerge as significantly upregulated gene by GATA3 overexpression in 5637 basal bladder cancer cells." (PMID 37250326, 2023). "That a joint analysis of p63 and GATA3 did not suggest a relevant contribution of GATA3 to the prognostic information further suggests that RNA based classifiers cannot easily be converted into a small set of IHC markers that will provide clinically relevant information on bladder cancer prognosis." (PMID 39539567, 2024). "GATA3 knockdown in bladder cancer lines also resulted in promotion of cell invasion and migration as well as induction of the expression of their related molecules, such as MMP-2 and MMP-9, while androgens did not significantly change the levels of GATA3 expression in these cells." (PMID 26770009, 2015).
bladder cancer (continued). "Therefore, we used gene expression data following the individual and combined overexpression of GATA3 and FOXA1 in the presence and absence of PPARɣ agonist to identify additional transcriptional regulators that may play a role in the activation of a luminal bladder cancer-specific gene expression." (PMID 27924948, 2016).
hypoparathyroidism (61 papers, 2008 to 2026). Hypoparathyroidism is an endocrine disorder in which the parathyroid glands in the neck do not produce enough parathyroid hormone (PTH). "GATA3 gene pathogenic variants are associated with Barakat syndrome, which is characterized by hypoparathyroidism, deafness, and kidney abnormalities." (PMID 40686918, 2025). "In humans, haploinsufficiency or mutations in GATA3, encoding a dual zinc finger transcription factor, cause the autosomal dominant disease known as hypoparathyroidism, deafness and renal dysplasia (HDR) syndrome or Barakat syndrome." (PMID 38353121, 2024). "The proband’s sister had a p.Trp329Gly missense in GATA3, linked to hypoparathyroidism, sensorineural deafness, and renal dysplasia; his daughter had a p.Ser251del in WDR45, associated with beta-propeller protein-associated neurodegeneration." (PMID 39062799, 2024). "For example, both Gata3 haploinsufficiency and Gata3 over-expression, as a result of gene duplication, cause human hypoparathyroidism, sensorineural deafness, and renal dysplasia (HDR) syndrome." (PMID 37090645, 2023). "The HDR syndrome is a rare autosomal dominant disorder characterised by Hypoparathyroidism, Deafness, and Renal dysplasia, and is caused by inactivating heterozygous germline mutations in the GATA3 gene." (PMID 37600721, 2023). "The HDR syndrome (OMIM 146255), also known as Barakat syndrome, is a rare autosomal dominant disorder characterised by Hypoparathyroidism (H), Deafness (D), and Renal dysplasia (R), and is caused by germline mutations of the GATA3 gene." (PMID 37600721, 2023). "HDR syndrome is a rare genetic disorder caused by mutations in the GATA3 gene and characterized by hypoparathyroidism, sensorineural deafness, and renal disease." (PMID 37908274, 2023). "Patient 15 presents a de novo heterozygous variant in the GATA3 gene, whose pathogenic variants are associated with hypoparathyroidism, sensorineural deafness, and renal dysplasia syndrome (MIM: # 146255)." (PMID 36979683, 2023). "Female genital tract malformations, such as uterus didelphys with septate vagina and septate uterus, have also been observed in patients with hypoparathyroidism, deafness, and renal dysplasia syndrome harboring GATA3 mutations." (PMID 35361250, 2022). "Haplo-insufficiency of the GATA3 gene causes hypoparathyroidism, sensorineural hearing loss, and renal disease (HDR) syndrome." (PMID 34349220, 2021). "In humans, haplo-insufficiency of the GATA3 gene causes hypoparathyroidism, sensorineural hearing loss, and renal disease (HDR) syndrome, also known as Barakat syndrome." (PMID 34349220, 2021). "In humans, mutation of the gene GATA3 associates with two highly variable birth defects that can disrupt development of the face, microsomia and Hypoparathyroidism, Deafness and Renal dysplasia (HDR) syndrome." (PMID 34033651, 2021). "GATA3 is upstream of Gcm2 and causes Gcm2 dysregulation; its haploinsufficiency causes the hypoparathyroidism, deafness, and renal anomaly syndrome, which results in these three pathologies." (PMID 32517664, 2020). "Barakat syndrome is an autosomal dominant disorder characterized by the triad of hypoparathyroidism, sensorineural deafness, and renal anomalies and is caused by mutations in GATA3 gene." (PMID 32155322, 2020). "In 20XX, she developed nephrocalcinosis and was confirmed to have a GATA3 mutation; hence, she was diagnosed with hypoparathyroidism, sensorineural deafness, and renal dysplasia syndrome." (PMID 33163915, 2020). "Patients with rare defects in the gene encoding GATA3 have hypoparathyroidism, sensorineural deafness, and renal disease (HDR) (MIM 146255) resulting from decreased GATA3 function." (PMID 31238969, 2019). "The latest report of HDR syndrome caused by the p.Arg367* mutation in the GATA3 gene is a male infant from a Turkish family, who presented hypoparathyroidism and renal anomalies, while auditory tests were normal." (PMID 30534854, 2018).
hypoparathyroidism (continued). "Gata3 haploinsufficiency causes human hypoparathyroidism, sensorineural deafness, and renal dysplasia (HDR) syndrome." (PMID 30295986, 2018). "HDR syndrome is a rare autosomal dominant disorder caused by mutations in the GATA3 gene and characterized by hypoparathyroidism, sensorineural deafness and renal abnormalities." (PMID 30534854, 2018). "Particularly interesting is the variant near GATA3 gene since mutations in this gene are the cause of hypoparathyroidism with sensorineural deafness and renal dysplasia." (PMID 30134803, 2018). "It is characterized by hypoparathyroidism, sensorineural deafness, and renal dysplasia, inherited dominantly, and is found to be related with GATA3 (GATA binding protein 3) gene mutations." (PMID 26777049, 2015). "Our results suggest new approaches to rescue diseases due to GATA-3 deficiency – such as in hypoparathyroidism, sensorineural deafness, and renal (HDR) syndrome – by OPG therapy." (PMID 26216189, 2015). "The GATA3 gene haploinsufficiency is the cause of hypoparathyroidism with sensorineural deafness and renal dysplasia also known as Barakat syndrome." (PMID 25016475, 2014). "Mutation of the transcription factor GATA3 in humans causes hypoparathyroidism, sensorineural deafness and renal dysplasia (HDR) syndrome, which displays a high degree of phenotypic heterogeneity." (PMID 23720234, 2013). "GATA3 haploinsufficiency causes hypoparathyroidism and hypocalcemia in the autosomal dominant HDR syndrome (hypoparathyroidism, sensorineural deafness and renal dysplasia) (OMIM#146255)." (PMID 24068962, 2013). "Haploinsufficiency of human GATA3 (due to loss-of-function mutation of GATA3) causes a dominantly-inherited syndrome of hypoparathyroidism, sensorineural deafness, and renal disease (HDR, OMIM #146255) also known as Barakat syndrome." (PMID 23659281, 2013). "Barakat syndrome (also known as HDR syndrome) is an autosomal dominant disorder characterized by hypoparathyroidism, sensorineural deafness, and renal disease caused by mutation of the GATA3 gene located at chromosome 10p15." (PMID 24527244, 2013). "Mutation of the transcription factor GATA3 in humans causes the highly variable hypoparathyroidism, sensorineural deafness and renal dysplasia (HDR) syndrome." (PMID 23720234, 2013). "In humans, mutations in Gata3 are associated with a syndrome of hypoparathyroidism, sensorineural deafness and renal disease." (PMID 22087235, 2011). "A novel mutation in the GATA3 gene that results in haplodeficiency causes HDR syndrome (hypoparathyroidism, deafness, renal dysplasia)." (PMID 20502531, 2010). "In humans, mutations in GATA3 are associated with HDR (hypoparathyroidism, sensorineural deafness, and renal anomaly) syndrome." (PMID 18404215, 2008). "In LER (CD−M2), Ush1c, Otogl, Gjb2, and Eps8 were associated with NSHL; Ush1c and Clrn1 with Usher syndrome, Six1 with branchiootorenal syndrome; Gjb2 with skin phenotype and HL; Gata3 with hypoparathyroidism, sensorineural hearing loss, and renal dysplasia; and Col9a2 with Stickler syndrome." (PMID 39684410, 2024). "Given the prominence of hearing loss and hypoparathyroidism, also assessing renal defects at neonatal stages should be informative for diagnosis, as might next-generation sequencing to ascertain mutations in GATA3." (PMID 38353121, 2024). "Conversely, in the second group, Patient 15, a carrier of a novel heterozygous variant in the GATA3 gene associated with hypoparathyroidism, sensorineural deafness, and renal dysplasia syndrome, will need to be constantly monitored over time to unveil possible early signs of hypoparathyroidism." (PMID 36979683, 2023). "GATA3 mutations cause hypoparathyroidism, deafness, renal dysplasia syndrome, and CAKUT." (PMID 35361250, 2022). "Furthermore, GATA3 is the causative gene for human hypoparathyroidism, deafness, and renal dysplasia (HDR) syndrome." (PMID 33805165, 2021).